ADAMTS13 (ADAM metallopeptidase with thrombospondin type 1 motif 13)
Diseases named in the same sentence as ADAMTS13 in open-access papers (continued):
Sharing a sentence is not in itself a finding about the gene and the disease.
COVID-19 (continued). "Our observations indicate that VWF, possibly perpetuated by (local) relative lack of ADAMTS13 activity, might play a critical role in the pathomechanism of COVID-19 being more than a marker of endothelial damage." (PMID 37333991, 2023). "Usually ADAMTS13 activity is not decreased during acute phase of inflammation but majority of patients with COVID-19 were presenting lower ADAMTS13 activity, which may be explained by underlying endothelial cell injury." (PMID 37074264, 2023). "Similarly, ADAMTS13 levels were reduced (p = 0.009) and the VWF/ADAMTS13 ratio was increased (p = 0.0004) in convalescent COVID-19 patients with dysregulated angiogenesis and immunothrombosis, while levels of PF4 (a putative protector of VWF) were also elevated (p = 0.0001)." (PMID 36926331, 2023). "Therefore, a potential target in the thrombophylactic treatment of COVID-19, could be the modulation of endothelial cell activation, in particular related to VWF and ADAMTS-13." (PMID 35482749, 2022). "However, ADAMTS13 levels and activities were unchanged within the overweight (25–29.9 kg/m2) and obese (>30 kg/m2) BMI groupings regardless of COVID-19 status." (PMID 35087853, 2021). "In addition, ADAMTS13 activity is not expected to significantly decrease in acute inflammation, yet the majority of COVID-19 patients had decreased ADAMTS13 activity, indicating a profound endothelial dysregulation or an intrinsic ADAMTS13 activity deficiency." (PMID 33709050, 2021). "However, to our knowledge, no study has specifically focused on VWF/ADAMTS13 axis changes of coagulation combined with thrombin and plasmin generation in COVID-19 (−) or COVID-19 (+) patient cohorts at the time of hospital presentation and admission." (PMID 35087853, 2021). "In contrast, the patient in case 2 had a family history significant for HUS, normal ADAMTS13 activity and stool infectious studies, a high titer of anti-CFH autoantibody, and slow but excellent response to eculizumab, all of which favor a diagnosis of aHUS, with likely COVID-19 trigger." (PMID 34903272, 2021). "However, in a recent study conducted by Escher and colleagues, no role of ADAMTS13 in the pathogenesis of COVID-19 coagulopathy was observed." (PMID 33357215, 2020). "In addition to VWF/ADAMTS13 axis dysregulation, plasma predictors of thrombosis and fibrinolysis potential, such as thrombin and plasmin generation, respectively, have not been well-defined in COVID-19 patients." (PMID 35087853, 2021). "In a sense, acquired TTP is caused by an abnormal ratio of vWF, which may be released in normal quantities, and nonfunctioning ADAMTS13, whereas in COVID-19, there is a massive release of ULvWF and regular or reduced levels of ADAMTS13, secondary to consumption, that result in microthrombosis." (PMID 34208470, 2021). "We provide representative gel analyses of patients with COVID-19 having increased VWF concentrations and antibodies to ADAMTS13, critically ill patients without COVID-19 and patients with acute TTP." (PMID 37380654, 2023). "Independent of COVID-19, VWF:AG and the VWF:AG/ADAMTS13 activity ratio increase with aging (≥65 years of age) and body mass index (BMI; >25 kg/m2)." (PMID 35087853, 2021). "The VWF/ADAMTS13 axis is significantly imbalanced in favor of higher VWF levels and activity and lower ADAMTS13 levels and activity in both acutely ill COVID-19 (−) and COVID-19 (+) non-survivors at the time of hospital admission." (PMID 35087853, 2021).
microangiopathic hemolytic anemia (74 papers, 2012 to 2026). "A rare inherited form of the disease known as congenital TTP (cTTP) or Upshaw–Schulman syndrome is caused by mutations in the ADAMTS13 gene, and typically presents in childhood, often before the age of 10." (PMID 41303245, 2025). "Congenital thrombotic thrombocytopenic purpura (cTTP) is an extremely rare recessively inherited disease linked to the mutation of ADAMTS-13, a gene coding for a von Willebrand factor (VWF)-cleaving protease (ADAMTS-13)." (PMID 39995752, 2025). "Congenital thrombotic thrombocytopenic purpura (cTTP; Upshaw-Schulman syndrome) is an ultra-rare disorder caused by severe deficiency of ADAMTS13, the metalloprotease responsible for cleaving ultra-large von Willebrand factor (UL-VWF) multimers." (PMID 41458739, 2025). "Congenital thrombotic thrombocytopenic purpura (cTTP), also known as Upshaw-Schulman syndrome, is a rare microangiopathic disorder caused by inherited mutations in the ADAMTS13 gene." (PMID 37822445, 2023). "Congenital thrombotic thrombocytopenic purpura (cTTP) is a rare autosomal recessive microangiopathic disorder caused by inherited mutations in the ADAMTS13 gene." (PMID 37822445, 2023). "TTP are mostly acquired forms due to the presence of ADAMTS-13 autoantibodies, whereas less than 5% of TTP are due to mutations in the ADAMTS13 gene (Upshaw-Schulman syndrome)." (PMID 35927768, 2022). "Congenital TTP (or Upshaw-Schulman syndrome) is a very rare, autosomal recessive disease, which is caused by homozygous or compound heterozygous ADAMTS13 mutations." (PMID 33732721, 2021). "TTP is a rare microangiopathic hemolytic anemia in which mutations of vWF protease (ADAMTS13) or autoantibodies against ADAMTS13 lead to the deposition of von Willebrand factor (vWF) multimers within capillaries." (PMID 33919576, 2021). "In less than 5% of cases, TTP is congenital (Upshaw-Schulman syndrome) due to mutations in the ADAMTS13 gene, with it being more severe in children and adolescents." (PMID 37359200, 2021). "More importantly, it was reported in compound heterozygosity with a further ADAMTS13 mutation in several Upshaw-Schulman syndrome (USS) patients." (PMID 33732721, 2021). "ADAMTS13:AC is lower in individuals with congenital ADAMTS13 gene mutations (Upshaw-Schulman syndrome) and individuals with acquired autoantibodies against ADAMTS13." (PMID 26580395, 2015). "Hereditary forms of TTP (e.g. Upshaw-Schulman syndrome) are due to a genetic deficiency of the metalloproteinase ADAMTS13." (PMID 25429351, 2014). "The rare congenital form of disease, also known as Upshaw-Schulman syndrome, is caused by a mutation of the gene coding for ADAMTS13 found on chromosome 9q34 and follows an autosomal recessive pattern of inheritance." (PMID 24288641, 2013). "Inherited TTP, also known as Upshaw-Schulman Syndrome, results from genetic mutations in the ADAMTS13 gene and represents approximately 10% of those patients with TTP." (PMID 22888446, 2012). "TTP is suspected when ADAMTS-13 activity is ≤ 10% and is typically acquired due to auto-antibodies against ADAMTS-13 (approximately 95% of cases) but can also be congenital (Upshaw-Schulman syndrome) due to mutations on the corresponding gene affecting ADAMTS-13 function." (PMID 40993743, 2025). "In the present two cases, severely reduced ADAMTS-13 activity and the presence of schistocytes or microangiopathic hemolytic anemia on the blood smear support the diagnosis of TTP." (PMID 35891176, 2022). "The congenital form is Upshaw Schulman syndrome and the acquired form of TTP is thought to be due to an autoantibody against ADAMTS13, and the inherited form is due to a genetic deficiency of ADAMTS13." (PMID 35949449, 2022). "Congenital or hereditary thrombotic thrombocytopenic purpura (cTTP) or Upshaw Schulman syndrome (USS, OMIM #274150) is a very rare disorder characterized by severe ADAMTS13 deficiency." (PMID 33732721, 2021).
microangiopathic hemolytic anemia (continued). "The treatment for Upshaw-Schulman syndrome (USS) is relatively simple, which is the supplementation of the deficient ADAMTS13 enzyme." (PMID 33072671, 2020). "Less than 5% of TTP cases are due to ADAMTS13 gene mutation (congenital TTP, Upshaw-Schulman syndrome (USS), an autosomal recessive disease presenting with early onset in childhood)." (PMID 31337190, 2019). "Upshaw-Schulman syndrome (USS), also called hereditary thrombotic thrombocytopenic purpura (TTP), is an autosomal-recessive trait associated with severely deficient plasma ADAMTS13 activity." (PMID 24936513, 2014). "The ADAMTS13 deficiency leads to the accumulation of high molecular weight vWF multimers, which in turn, form platelet rich clots that cause TMA lesions and microangiopathic hemolytic anemia." (PMID 25429351, 2014). "Indeed, many patients with TTP are initially diagnosed with microangiopathic hemolytic anemia and are only diagnosed with TTP after delayed laboratory results of deficient ADAMTS13 activity are received." (PMID 40863221, 2025). "Constantly deficient ADAMTS13 activity without ADAMTS13 inhibitors and evidence of homozygosity for a rare complex ADAMTS13 allele led to the diagnosis of congenital thrombotic thrombocytopenic purpura (cTTP)." (PMID 33732721, 2021). "Hereditary thrombotic thrombocytopenic purpura (hTTP), also known as Upshaw–Schulman syndrome, is a rare genetic disorder caused by mutations in the ADAMTS13 gene that leads to decreased or absent production of the plasma von Willebrand factor (VWF)-cleaving metalloprotease ADAMTS13." (PMID 37895305, 2023). "Regarding the mechanisms of ADAMTS13 reduction, biological testing to document microangiopathic hemolytic anemia was not performed in our study." (PMID 41160661, 2025). "Congenital TTP (cTTP), also referred to as Upshaw-Schulman syndrome (USS), is a very rare autosomal recessive disorder caused by biallelic homozygous or compound heterozygous variants within the ADAMTS13 gene, leading to severely decreased or absent proteolytic activity." (PMID 35479064, 2022). "Low but not deficient ADAMTS13 level of patients besides the absence of ADAMTS13 inhibitors (where measured) excluded the diagnosis of TTP, while based on the normal levels of ADAMTS13 activity of the healthy family members we ruled out the possibility of Upshaw-Schulman syndrome." (PMID 25496981, 2014). "If TTP is confirmed by ADAMTS-13 activity ≤ 10%, presence of ADAMTS-13 autoantibodies and no family history suggestive of an Upshaw-Schulman syndrome, corticosteroid therapy with the addition of rituximab is recommended during both first and relapse episodes." (PMID 35927768, 2022).
Sepsis (73 papers, 2009 to 2026). Sepsis is defined as life-threatening organ dysfunction caused by a dysregulated host response to infection. "A decrease in ADAMTS-13 levels correlates with a heightened risk of mortality in patients facing sepsis and septic shock." (PMID 40244141, 2025). "Partial deficiencies of ADAMTS13 have been observed in diseases sharing inflammatory states, including cardiovascular diseases, severe sepsis, and septic shock." (PMID 40362344, 2025). "ADAMTS-13 deficiency, leading to ultra large von Willebrand factor multimers and thrombotic microangiopathy in sepsis, was associated with sepsis severity and poor prognosis." (PMID 36836706, 2023). "A previous study reported that patients with high VWF:Ag/ADAMTS13:AC levels had a high risk of sepsis with MOF." (PMID 36829443, 2023). "Additional studies have shown that VWF and ADAMTS-13 levels are clearly associated with disease severity and/or poor prognosis in sepsis." (PMID 37886991, 2023). "The release of vWF multimers in the context of sepsis-associated ADAMTS13 deficiency determines microvascular thrombosis with an impact on organ dysfunction severity." (PMID 36675530, 2023). "Acquired plasma protease ADAMTS13 deficiency has also been described in sepsis and systemic inflammatory response syndrome." (PMID 35949449, 2022). "Consequentially, an increased vWF:Ag/ADAMTS13 ratio has been repeatedly associated with severity of shock and organ failure as well as increased mortality in sepsis." (PMID 35551628, 2022). "Low ADAMTS13 levels have been associated with increased mortality in patients suffering from sepsis or in septic shock." (PMID 36574434, 2022). "ADAMTS13 activity below 45% has already been associated with increased mortality in sepsis, activity below 30% with significantly higher systemic inflammation (i.e., IL-6 concentrations) and greater incidence of overt DIC." (PMID 35551628, 2022). "The extent of reduced ADAMTS13 antigen levels and activity appeared strongly associated with sepsis severity and prognosis." (PMID 33606732, 2021). "Recently, ADAMTS13 deficiency has been reported in cases of severe sepsis, disseminated intravascular coagulation, complicated malarial infection, and systemic inflammation superimposed on advanced cirrhosis." (PMID 34819564, 2021). "During sepsis and trauma, several authors have reported a reduction of ADAMTS13 activity in plasma and its association with disease severity and outcome." (PMID 34343182, 2021). "In fact, an increased vWF:Ag/ADAMTS13 ratio has been repeatedly associated with the severity of shock and organ failure as well as increased mortality in sepsis." (PMID 32122366, 2020). "More recently, it has been demonstrated that a significant deficiency of ADAMTS13 also appears in sepsis." (PMID 32122366, 2020). "Recently, ADAMTS-13 deficiency has been described in patients with severe sepsis and systemic inflammatory response syndrome, leading to an increased interest in the role of plasma exchange as an adjunct in the treatment of sepsis." (PMID 25527094, 2014). "For example, in some cases of severe sepsis, attenuation in the release of ADAMTS13 results in the formation of large vWF multimers causing disseminated microvascular thrombosis and organ failure." (PMID 24408224, 2014). "Several investigators postulated that ADAMTS13 deficiency was associated with AKI in patients with sepsis." (PMID 25960882, 2014). "We conducted this study to detect ADAMTS-13 deficiency and its impact on in-hospital mortality in pediatric patients with severe sepsis." (PMID 23537039, 2013). "A previous study in 109 patients with sepsis-induced DIC also found that 17 patients had severe ADAMTS13 functional deficiency, and also exhibited a TTP-like clinical presentation." (PMID 24238574, 2013). "Synthetic granulocyte elastase inhibitors inhibit granulocyte elastase, an enzyme implicated in causing ADAMTS-13 deficiency in patients with sepsis." (PMID 23537039, 2013).
Sepsis (continued). "Few studies have also shown that reduced ADAMTS-13 is associated with a poor survival rate in sepsis." (PMID 23537039, 2013). "Our results revealed that pediatric patients with severe sepsis had a high incidence of ADAMTS-13 deficiency." (PMID 23537039, 2013). "Based on the background of association of ADAMTS-13 with sepsis, we conducted this study to detect ADAMTS-13 deficiency in pediatric patients with severe sepsis." (PMID 23537039, 2013). "Although these studies gave interesting insight into ADAMTS13 levels during sepsis, clinical relevancy, prognostic association and mechanisms of a potential deficiency remain uncertain." (PMID 24238574, 2013). "The association between functional partial deficiency of ADAMTS13 and clinical prognosis factors in sepsis raises the question of the relevance of this metalloprotease as a passive marker or, in contrast, as an actor in the pathophysiology of organ failure." (PMID 24238574, 2013). "Majority of the pediatric patients admitted to hospital with severe sepsis exhibit ADAMTS-13 deficiency." (PMID 23537039, 2013). "Notably, a deficiency of ADAMTS13 occurs in other inflammatory conditions such as cardiovascular diseases, severe sepsis and septic shock, myocardial infarction, severe Plasmodium falciparum malaria, alcoholic hepatitis, and anti-phospholipid syndrome." (PMID 40362344, 2025). "Lower ADAMTS13 activity due to sepsis is also associated with a poor prognosis." (PMID 39039520, 2024). "Acquired ADAMTS-13 deficiency in pediatric patients with severe sepsis." (PMID 35223703, 2022). "Interestingly, baseline ADAMTS-13 levels were similar in all patients in both arms, suggesting a possible association with severity of illness, as suggested in prior reports with sepsis." (PMID 32831133, 2020). "ADAMTS-13 has been studied recently in adult and pediatric patients with severe sepsis, and it has been shown that patients with severe sepsis have ADAMTS-13 deficiency, and that it may affect in-hospital mortality." (PMID 31434239, 2019). "Previous studies have found an association between sepsis and reduced levels of ADAMTS13." (PMID 28296884, 2017). "Cleavage of ADAMTS13 by leukocyte elastase together with thrombin and plasmin cause a severe secondary ADAMTS13 deficiency, and there may be a clinical correlation with renal endothelial cells dysfunction in patients with sepsis-induced DIC." (PMID 27408725, 2015). "ADAMTS13 (a disintegrin and metalloprotease with thrombospondin type 1 repeats, member 13) deficiency has been reported in patients with sepsis but its clinical relevance and pathophysiology remain unclear." (PMID 24238574, 2013). "Reduced ADAMTS-13 has also been observed in severe sepsis and is associated with poor survival." (PMID 23537039, 2013). "In pediatric patients with severe sepsis, ADAMTS13 deficiencies have also been reported." (PMID 24238574, 2013). "Indeed, sepsis may lead to acquired a disintegrin and metalloprotease with thrombospondin type I repeats-13 (ADAMTS13) deficiency since inflammatory mediators can inactivate ADAMTS13." (PMID 35721048, 2022). "Interestingly, a deficiency of ADAMTS13 is also detectable in sepsis." (PMID 35551628, 2022). "Furthermore, because of early recognition and improved care of patients with sepsis, the survival may have improved in those who were ADAMTS-13 deficient." (PMID 23537039, 2013). "In a study conducted in Japan, decreased ADAMTS-13 activity ( less than 5%) was found in 15.6% of patients with sepsis induced disseminated intravascular coagulation; whereas in USA a study showed that 31% of patients with severe sepsis had severe ADAMTS-13 deficiency." (PMID 23537039, 2013). "First, normal ADAMTS13:Ag levels found in our cohort suggested that ADAMTS13 functional deficiency was mainly related to a qualitative defect and not to a quantitative defect secondary to a synthesis/secretion deficiency or to a degradation process mediated by sepsis-related enzymes." (PMID 24238574, 2013).